CTBS (chitobiase)
Description:
Reducing-end exoglycosidase involved in glycan degradation. Hydrolyzes N,N'-diacetylchitobiose (GlnNAc2) and higher chitin-oligosaccharides (GlcNAc(n)) to monomeric GlcNAc acting on reducing-end residues. During N-linked glycoprotein degradation, it cleaves single GlcNAc molecules uniquely from the reducing end of N,N'-diacetylchitobiose units linking oligosaccharides to proteins, and therefore it functions after cleavage of the Asn-GlcNAc bond and asparagine removal by glycosylasparaginase (By similarity).
Synonyms: CTB
Tractability: Antibody: UniProt predicts a signal peptide or a membrane-spanning region. PROTAC: its protein half-life has been measured.
Gene: Protein-coding gene on chromosome 1 (84,549,611 to 84,574,480, reverse strand). Ensembl gene ENSG00000117151.
Subcellular location: Lysosome
Subcellular location (Human Protein Atlas): Cytosol
Gene Ontology:
Molecular function: hydrolase activity, acting on glycosyl bonds; chitinase activity; chitin binding; hydrolase activity, hydrolyzing O-glycosyl compounds
Biological process: carbohydrate catabolic process; chitin catabolic process; oligosaccharide catabolic process; carbohydrate metabolic process
Cellular component: extracellular region; lysosome
Genetic constraint (gnomAD): Loss-of-function variants: 26 observed, 33.28 expected, observed/expected ratio (o/e) 0.78, 90% interval 0.57 to 1.08. The upper end of that interval is the gene's LOEUF score, 1.08, which puts it in group 4 of 6, group 1 being the genes least tolerant of losing a copy. Missense variants: 393 observed, 375.25 expected, observed/expected ratio (o/e) 1.05, 90% interval 0.96 to 1.14. Synonymous variants: 123 observed, 132.8 expected, observed/expected ratio (o/e) 0.93, 90% interval 0.8 to 1.08.
Homologues: Orthologues: chimpanzee CTBS (98% identical), macaque CTBS (95% identical), guinea pig CTBS (86% identical), rabbit CTBS (81% identical), mouse Ctbs (79% identical), rat Ctbs (76% identical), dog CTBS (76% identical), pig CTBS (70% identical), zebrafish ctbs (62% identical), tropical clawed frog ctbs (59% identical), tropical clawed frog gng5 (57% identical), Drosophila melanogaster Cda5 (29% identical), and 1 more. Paralogues in human: CHIA (22% identical), CHI3L1 (21% identical), CHI3L2 (21% identical), OVGP1 (21% identical), CHIT1 (20% identical), CHID1 (15% identical).
Diseases named in the same sentence as CTBS in open-access papers:
CTBS is named in the same sentence as 5 diseases in open-access papers, as found by Europe PMC text mining. Sharing a sentence is not in itself a finding about the gene and the disease. The quoted sentences say what the papers report.
cancer (1 paper, 2022). A tumor composed of atypical neoplastic, often pleomorphic cells that invade other tissues. "The separationwas driven primarily by CD9 (importance = 0.37), TENX (importance= 0.32), and di-N-acetylchitobiase (DIAC, importance = 0.28), withboth TENX and DIAC showing a downregulation with disease progressionand CD9 showing a stronger upregulation in early- than late-stagepancreatic cancer." (PMID 35605973, 2022).
infection (1 paper, 2024). The state of being infected such as from the introduction of a foreign agent such as serum, vaccine, antigenic substance or organism. "Mucin-derived sugars could be taken up by the mussel through its SWEET importer and degraded in the cytoplasm to GlcNAc by the chitobiase CTBS, as both genes were upregulated by the host in early and mid infection stages." (PMID 39242818, 2024).
CTBS also shares sentences with these, for which no sentence is quoted: prostate carcinoma (1 paper); thyroid cancer (1); tumor (1).